TNF (tumor necrosis factor)
Diseases named in the same sentence as TNF in open-access papers (continued):
Sharing a sentence is not in itself a finding about the gene and the disease.
COVID-19 (continued). "TNF-α plays a critical role in COVID-19’s inflammatory response, especially in respiratory issues and lung damage." (PMID 39940645, 2025). "Recent studies on SARS-CoV-2 revealed that COVID-19-associated cytokine storms (CSs) show elevated levels of IL-1 beta, IL-6, CXCL10, TNF alpha, IFN gamma, MIP 1 alpha, and 1 beta, as well as MCP-1, GM-CSF, VEGF, and IL-10." (PMID 40358160, 2025). "In contrast, the adaptative immune response induces a reduction in absolute lymphocyte count in COVID-19 as a consequence of extended TNF-α-induced apoptosis, peripheral consumption, a direct ACE-2-cytopathic effect, or through interaction with CD147." (PMID 40332089, 2025). "Upon reviewing the literature, we postulate that tumor necrosis factor (TNF) and its receptors, CD40L/CD40, along with the cell surface receptor sTREM-2, are implicated in COVID-19-induced CSVD." (PMID 40491910, 2025). "Elevated TNF-α has been detected in COVID-19-related ARDS and in IPF lung tissue, suggesting that this cytokine plays a shared pathological role." (PMID 40806851, 2025). "Observational studies indicate that autoimmune patients on anti–TNF-α therapy have reduced severe COVID-19 incidence, aligning with our findings linking IL-6 and TNF-α to infection susceptibility in SLE." (PMID 40643149, 2025). "Immune dysfunction is pivotal in the development of severe COVID-19, as evidenced by the common observation of higher pro-inflammatory cytokine levels, including IL-6, TNF-α, and IFN-γ, in such cases." (PMID 40137715, 2025). "Reduction in total CD45+, CD4+, and CD8+ T-cell frequencies was observed in both COVID-19+ and UN samples over the culture period; TNF-α+-producing CD45+ cells also decreased, but the change was not significant." (PMID 40698364, 2025). "COVID-19's cytokine storm, characterised by IL-6, TNF-α, and IL-1β elevation, damages the neurovascular unit and increases vascular permeability." (PMID 41503306, 2025). "The cytokine storm seen in severe COVID-19—involving elevated levels of interleukins (IL-6, IL-1β) and tumor necrosis factor-α (TNF-α)—increases thrombin generation and fibrin deposition." (PMID 41458994, 2025). "As a result, MSCs will increase the number of lymphocytes and regulatory DCs, boosting their antiviral properties, and resulting in lower IL-6, CRP, IL-8, and TNF levels in COVID-19 patients." (PMID 40895261, 2025). "Six genes, including TNF, CXCL8, IL-6, IL-1β, IL-2, and IL-10, were associated with three major signaling pathways: the COVID-19 adverse outcome pathway, an overview of pro-inflammatory and pro-fibrotic mediators, and the interleukin-10 signaling pathway." (PMID 40166075, 2025). "Associations between specific microbial ASVs and blood levels of TNF-α and IP-10 in long COVID-19 were also sex-dependent." (PMID 40723800, 2025). "(2021) revealed increased levels of IFN-α and, TNF-α in patients who died from COVID-19, supporting the idea that inflammatory cytokines play a key role in disease progression." (PMID 40881695, 2025). "Owing to this critical role of TNF-α in prompting COVID-19-related cytokine storm syndrome, it is crucial to screen for new approaches as anti-TNF therapy." (PMID 39854441, 2025). "Our results also showed an increase in circulating IL-6, IL-10, and TNF-α levels in critical COVID-19 patients after 10 days of hospitalization, highlighting the importance of quantifying these cytokines longitudinally in COVID-19 patients." (PMID 40508859, 2025). "Genes within this pathway, including IL1A and TNF, were more expressed in moderate and severe COVID-19 cases compared to RSV." (PMID 39877087, 2025). "With an available COVID-19 dataset, we show CD4+ T cell dysfunction in severe COVID-19 as TNF-α/TNF receptor 1-dependent immune pathways." (PMID 40429912, 2025). "Patients with COVID-19 exhibit cytokine storm and abnormally high levels of inflammatory mediators, including IL-6, tumor necrosis factor-alpha (TNF-a), and C-reactive protein (CRP)." (PMID 41002604, 2025).
COVID-19 (continued). "Tumour necrosis factor-alpha (TNF-α) plays a central role in the cytokine storm characteristic of severe COVID-19." (PMID 40481519, 2025). "Our data reveal a shift towards a pro-inflammatory M1 phenotype in severe COVID-19 cases, with elevated expression of TNFα, IL1β, CCL2, and CCL3, which are markers of classical activation and inflammation." (PMID 39928675, 2025). "Numerous studies have reported increased serum levels of IL-6 in COVID-19 patients, with its release significantly amplified by IL-1β and TNF-α during early inflammation." (PMID 40219044, 2025). "Acute COVID-19 features an imbalanced host response marked by elevations of IL-1β, IL-6, IL-8, TNF-α and interferon-inducible chemokines (e.g., CXCL9/CXCL10) that govern myeloid recruitment, T-cell positioning, angiogenesis, and tissue remodeling." (PMID 41440526, 2025). "The result supported previous studies, thus suggesting that TNF is a potential biomarker to predict COVID-19 severity." (PMID 38187222, 2024). "The source of ROS in the HPMVECs with COVID-19 is unclear; therefore, we assessed TNF-α levels in all serum samples and found that it was within the range of 11.2–18.5 pg/ml for patients with COVID-19 and undetectable in healthy controls." (PMID 38771750, 2024). "Several Ayurvedic medical formulations like Swarna Bhasma and Rajata Bhasma have been reported as efficient treatments against COVID-19 due to their capacity to lower inflammatory markers in plasma like interleukins, interferons, and TNF levels." (PMID 39791040, 2024). "Two studies that evaluated CMIR immediately after a third dose of COVID-19 vaccine found that those on anti-TNF therapy mounted similar or lower CMIR compared with healthy controls." (PMID 38349178, 2024). "Results showed that levels of IL-1β, IL-6, and TNF-α were significantly elevated after treatment with COVID-19 EVs." (PMID 39475319, 2024). "The dysregulated immune response characteristic of severe COVID-19 involves a cytokine storm, marked by an excessive release of proinflammatory cytokines (e.g. IL-6,TNF-alpha)." (PMID 39359765, 2024). "In COVID-19 patients, the immune response to the viral infection can lead to elevated levels of serum cytokines, including Interleukin-6 and Tumor necrosis factor." (PMID 38616997, 2024). "The levels of cytokines, including IL-6, IL-1β, IL-10, IFN-γ, tumor necrosisfactor-α (TNF-α), and colony-stimulating factor (CSF), gradually increase with theseverity of COVID-19 and play a crucial role in the immune response to SARS-CoV-2 infection." (PMID 39759510, 2024). "In this account, studies show that in patients with COVID-19, the level of tumor necrosis alpha (TNFα) and interleukin-6 (IL-6) is high and in severe cases of COVID-19, the production of IL-6, TNF-α, and other cytokines increases profoundly." (PMID 39118801, 2024). "They note that severe COVID-19 patients exhibit extremely high levels of proinflammatory cytokines like IL-6 and TNF-α." (PMID 39350850, 2024). "In this study, we aimed to find out the association of genetic polymorphisms in TNF-α, IL-8, IL-10 and CXCR-2 genes with susceptibility to and mortality of COVID-19." (PMID 38544825, 2024). "TNF levels are elevated in COVID-19 patients, with higher baseline levels correlating with increased mortality risk." (PMID 39459457, 2024). "Serum TNF-α levels have been observed to be elevated in COVID-19 patients and are higher in critically ill patients." (PMID 39335569, 2024). "It improves diabetic complications and T cell function in patients with COVID-19 by reprogramming dendritic cell metabolism, inducing tolerance, and reducing pro-inflammatory factors such as IL-2 and tumor necrosis factor alpha." (PMID 39845945, 2024). "Clinical data has demonstrated that TNF is commonly present in the blood and diseased tissues of COVID-19 patients, with its levels increasing as the disease progresses." (PMID 39130417, 2024).
COVID-19 (continued). "It is noteworthy that the release of inflammatory cytokines and PANoptosis exhibit reciprocal causation: the synergism of TNF-α and IFN-γ initiates PANoptosis in COVID-19, and PANoptosis, in turn, triggers cytokine storm." (PMID 38555477, 2024). "This cross-disease study identified that interferon-gamma and TNF-alpha signaling in macrophages were crucial in the inflammatory phenotype observed in severe COVID-19." (PMID 38542251, 2024). "In COVID-19 patients, the cytokine storm exposes the endothelium to pro-inflammatory cytokines such as IL-6, interleukin-1β (IL-1β), and tumor necrosis factor-α (TNF-α)." (PMID 40276305, 2024). "A heatmap was constructed for joint analysis of the gene expression levels of cGAS and STING and plasma levels of IFN-α, TNF-α and IL-6 in acute COVID-19 and in the post-COVID-19 period." (PMID 38424312, 2024). "A meta-analysis that included 13 studies in COVID-19 patients where MT was administered showed that there were significant reductions in TNF-α and IL-6 levels." (PMID 38674128, 2024). "Studies have demonstrated that severe COVID-19 patients exhibit extremely high levels of proinflammatory cytokines like IL-6 and TNF-α, which contribute to chronic inflammation and oxidative stress." (PMID 39350850, 2024). "COVID-19 induces uncontrolled inflammation, a so-called cytokine storm, including IL-6, IL-1b, IL-2, IL-10, TNF-α and monocyte chemoattractant protein (MCP-1)." (PMID 38732160, 2024). "By ingesting 10 g of glutamine three times daily, COVID-19 patients presenting pulmonary infections can reduce their concentrations of IL-6, TNF-a, and hs-CRP and increase their appetite." (PMID 38390861, 2024). "Elevated levels of TNF-α remained stable in individuals with ongoing postacute COVID-19 sequelae who experienced prolonged symptoms until 10 months after COVID-19 testing." (PMID 38550672, 2024). "Elevated levels of IL-6, IL-10, and TNF-α have been shown to predict clinical progression to severe forms of COVID-19." (PMID 39203987, 2024). "Age exhibited negative correlations with levels of pro-inflammatory cytokines, including IFN-γ, TNF, IL-2, and IL-6, following COVID-19 vaccination." (PMID 38909235, 2024). "TNF-α induction by LPS alone in the whole blood of the MIS-C group was also much weaker than that observed in blood samples from the control respiratory COVID-19 patients and other paediatric admission patients." (PMID 38762592, 2024). "Several treatments, including TNF-antagonizing (anti-TNF) therapies, impair the humoral immune response induced by COVID-19 mRNA vaccines after two and three vaccine doses." (PMID 39066413, 2024). "interleukin-6 (IL-6), IL-10, tumor necrosis factor (TNF)-α, IL-1β, IL-4, IL-8 and IL-17 are associated with increased severity as well as mortality in COVID-19 patients." (PMID 38544825, 2024). "In this Swedish nationwide study including IRD patients three and four COVID-19 vaccine doses were immunogenic in patients treated with IL6r inhibitors, TNF-inhibitors, JAK-inhibitors, and IL12/23/17-inhibitors but not in rituximab." (PMID 38441463, 2024). "For example, elevated levels of RANTES, TNF-α, and MCP-3 have been associated with a lethal cytokine storm in COVID-19 patients." (PMID 39065791, 2024). "Interleukin (IL)-6 and tumor necrosis factor (TNF)-α have been considered by many as major cytokine culprits in the pathogenesis of this COVID-19-induced hyper-inflammation." (PMID 36445625, 2024). "The increased expression of pro-inflammatory cytokines IL-6, IL-1β, and TNF-α in COVID-19 patients compared to the control group confirms the sequence of events following NF-κB activation." (PMID 39201618, 2024). "In the CoVonly group receiving only the third booster dose of COVID-19 vaccine, we found, on 1 day (d1) post-immunization, a strong increase of the cytokines IL-15, IL-6, TNF-α and IFN-γ as well as of the chemokine CXCL10." (PMID 39340080, 2024).
COVID-19 (continued). "More interestingly, E protein strongly up-regulated TNF production, one of the most prominent cytokines predicting COVID-19 severity and death." (PMID 38928376, 2024). "Several different therapies, including steroids, IL-6-inhibitors, JAK-inhibitors, IL-1 receptor antagonists, and TNF-α inhibitors, have been reported to be beneficial in the treatment of selected groups with COVID-19." (PMID 38985797, 2024). "Cytokine storms, characterized by excessive release of inflammatory cytokines like IL-1β, TNF-α, IL-6, and IFN-γ, are associated with severe COVID-19 and can suppress the HPT axis, leading to decreased TSH secretion." (PMID 40735669, 2024). "IL-6 and TNF-α are elevated in the blood and diseased tissue of patients with severe COVID-19 and are key cytokines for the development of cytokine storms." (PMID 38383655, 2024). "Data from patients previously treated with anti-TNF therapy showed poorer COVID-19 outcome rates and reduced mortality compared with other immunosuppressive regimens." (PMID 39118801, 2024). "Levels of cytokines IL-1β, IL-6 and TNFα and levels of cortisol levels according to COVID-19/PASC status." (PMID 38348267, 2024). "The elevated serum levels of IL-6, IL-10, and TNF-α have been correlated with disease severity and mortality in COVID-19 patients." (PMID 38932387, 2024). "The NF-κB transcription factor is activated by cytokines such as IL-1β, IL-6 and TNF-α, which are elevated in severe COVID-19." (PMID 39051370, 2024). "Another study has expanded results with elevated levels of plasma cytokines (IL-2, IL-7, IL-10, G-CSF, IP-10, MCP-1, MIP-1α, and TNF-α) in COVID-19 patients requiring Intensive Care Unit (ICU) admission compared to non-ICU patients." (PMID 38568894, 2024). "Specifically, IL-1β, TNF-α and IL-6, all of which are elevated in COVID-19, are potent activators of the p38 MAPK signalling cascade, which itself leads to further production of these cytokines." (PMID 39051370, 2024). "This process results in the development of the acute respiratory distress syndrome (ARDS) in the COVID-19 patients, and it is regulated by cytokines, such as IL-1β and TNF-α." (PMID 38999930, 2024). "Soluble TNFRI was significantly associated with death in COVID-19 patients (p < 0.001), and the ratios TNFRI/TNFα and TNFRI/TNFRII also depicted significant differences between the two groups (p < 0.001)." (PMID 39335653, 2024). "Considering that ORF3a stimulates NF-κB to induce cytokine production such as TNFα and IL-6, and that elevation of TNFα and IL-6 are two strong and independent survival predictors of patients with COVID-19, targeting these cytokines is also appealing." (PMID 38251382, 2024). "Higher levels of cytokines such as IL-6, IL-10, and TNF-α were observed in patients with severe COVID-19 compared to those with a mild and moderate course of COVID-19." (PMID 39063142, 2024). "Among them were also the alleles with high expression of TNF -308 (A) and IFNG +874 (T) that correlated positively with COVID-19 mortality." (PMID 38675991, 2024). "While it has been previously documented that TNF-α and IFN-γ are associated with mortality during COVID-19, a novel finding from our study is the association of amphiregulin with VFDs and development of fibroproliferation." (PMID 39106254, 2024). "Pronounced expression of complement proteins (C1q, C3, C3b, C4, C5) and inflammatory cytokines (TNF, IL-1α, and IL-17A/E) was detected in the fetal compartment of COVID-19-affected pregnancies." (PMID 39390219, 2024). "Using TNF-α inhibitors or blockers to treat COVID-129 can prevent mortality in severe COVID-19 patients." (PMID 39273479, 2024). "In order to test the potential impact of RIC in the setting of COVID-19, we selected a panel of pro-inflammatory cytokines that included IL-6, TNF-α, IL-1β, and IFN-γ." (PMID 36445625, 2024).
COVID-19 (continued). "A clinical study characterizing plasma immune profiles of individuals with TB and COVID-19 versus singular TB or COVID-19 discovered an immune signature composed of TNF-α, MIP-1β, and IL-9 that discriminated co-infection from COVID-19 alone." (PMID 38966641, 2024). "Combinatorial blockade of IL-6 and TNF-α results in a significant increase of cardiomyocyte viability, indicating an opportunity for therapeutic intervention in severe COVID-19." (PMID 38041432, 2024). "There is a notable decrease in anti-inflammatory microorganisms, such as Faecalibacterium prausnitzii and Eubacterium rectale, in COVID-19 patients, which corresponds with elevated levels of tumor necrosis factor (TNF), interleukin-10 (IL-10), and CXCL10." (PMID 38779486, 2024). "This study is consistent with a high level of Tumor Necrosis Factor α (TNF α) observed in OE samples from COVID-19-suffering patients and in ALI and iALI-infected cells." (PMID 38543591, 2024). "Stimulation of peripheral blood mononuclear cells from COVID-19 patients with helminth antigens is associated with reduced IFN-γ and TNF-α production and higher IL-10 levels." (PMID 38727220, 2024). "Other components, such as interleukins (IL-2, IL-6, IL-7, IL-10) and TNF-α are connected to severe COVID-19 symptoms, where cytokine storm (a sudden increase in cytokines) occurs instead of a healthy immune response (Fricke-Galindo and Falfán-Valencia 2021)." (PMID 38240884, 2024). "TNF-α, which regulates the inflammatory processes of infectious diseases, had its levels elevated in patients with COVID-19 and were higher in severe disease, resulting in a poor prognosis." (PMID 38707035, 2024). "TNF-a’s contribution to the severity of COVID-19 is well-documented, and its elevation in severe cases suggests a significant role in mediating the disease’s immunopathological processes." (PMID 39203987, 2024). "As patients recuperate from COVID-19, cytokine levels including TNF-α, TGF-b, IFN-g, IL-1b, IL-2, and IL-4 subside." (PMID 38844850, 2024). "In the individuals with severe COVID-19, we found that the autoantibody levels of IL-1α, IFNα2, TNFα, osteopontin, and IFNβ showed a high correlation with each other." (PMID 38491326, 2024). "Concerning neuroinflammatory process, cytokines TNF-α (tumor necrosis factor) and IL-6, which are upregulated in COVID-19, are also present in major depressive disorder and Alzheimer’s disease." (PMID 38313024, 2024). "Multiple proinflammatory cytokines were found elevated in the sera of COVID-10 patients, among which are IL-1β, IL-6, and TNF-α, which correlated with COVID-19 severity and mortality." (PMID 38183501, 2024). "In opposition, TNFR2, the other receptor of TNF-α, reduced hyperinflammation in COVID-19 acute respiratory distress syndrome (ARDS) after administering umbilical cord-derived mesenchymal stem cells." (PMID 38540252, 2024). "MiR-103a-3p targets SERPINE 1 (coding protein plasminogen activator inhibitor, PAI-1) and TNF genes In our study, miR-103a-3p levels were lower in COVID-19 patients compared with controls, although the top quartiles overlapped with controls." (PMID 39237986, 2024). "At day 6, the pro-inflammatory cytokine production pathways, such as cytokine–cytokine receptor interaction and TNF signaling, were ranked high, followed by virus pathways such as coronavirus disease—COVID-19." (PMID 39057755, 2024). "Since IL-6 and TNF-alpha are inflammatory cytokines that increase ROS, their upregulation in COVID-19 leads to increasingly depleted GSH and increasingly high ROS." (PMID 38539805, 2024). "The production of CRP by hepatocytes is stimulated by cytokines like interleukin‐6 (IL-6) and tumor necrosis factor-α (TNF-α) during COVID-19 development." (PMID 38184750, 2024). "A serum cytokine analysis, involving 207 COVID-19 patients, presented an elevation in levels of TNF-α in those with severe COVID-19." (PMID 38675414, 2024).